SMO (smoothened, frizzled class receptor)
Diseases named in the same sentence as SMO in open-access papers (continued):
Sharing a sentence is not in itself a finding about the gene and the disease.
tumor (continued). "The upregulation of SMO (smoothened) and LYN suggests that ciBMSCs exhibit features of chondrocytes and CAFs, potentially contributing to tumor progression by remodeling the extracellular matrix or secreting cytokines." (PMID 40809351, 2025). "Receptor Smoothened (SMO, SE = 4.8) activation by SHH ligands promotes tumor growth, while SHH/SMO pathway inhibition by the SMO antagonist, LDE225, in CAFs impairs tumor growth." (PMID 38892190, 2024). "While there is no recurrent gene amplification that was observed, the following genes were amplified in two tumor samples: MET, SMO, ERBB2, BRAF, EZH2, SRSF2, CUX1, and CEBPA." (PMID 38164123, 2024). "SHH signalling inhibitors effectively dismantle GBM cancer stem cells (CSCs) and prevent tumour recurrence by targeting SHH ligands, SMO, and GLI1 transcription factors at multiple points in the pathway." (PMID 39568072, 2024). "In situ hybridization further confirmed significant expression of SHH pathway proteins, including SMO, GLI1, GLI3, and SUFU, indicating an active role of SHH signalling in promoting tumour cell proliferation and maintenance." (PMID 39568072, 2024). "CGP of PCL tissues revealed the tumor to be wildtype for CD79B, MYD88, CARD11, and TNFAIP3, with genomic alterations detected in SMO, CIITA, ETS1, HST1H1D, and SOCS1." (PMID 36342081, 2023). "Four target sequences had been previously detected in tumor DNA by standard-of-care (SNVs in either the CTNNB1, SMO, or KDM6A genes)." (PMID 37046633, 2023). "Regarding the distribution of mutations according to tumor grades and subtypes, all mutations were present in most subtypes and grades analyzed, except for SMO L412F which was absent in grade II patients, which could be partly due to the reduced size of our cohort." (PMID 38259646, 2023). "Recently, researchers combined the SMO inhibitor MRT-92 and a Proteolysis Targeted Chimeras (PROTACs)-derived BRD4 degrader (MZ1), to treat the tumor and found that it remarkably suppressed tumor growth." (PMID 35267473, 2022). "In BC xenograft tumors, it significantly reduces tumor growth, which is accompanied by decreased PTCH, SMO, Gli1, and Gli2 expression." (PMID 34381705, 2021). "Homeobox A1 (HOXA1), an oncogene motivating tumor growth and tumor motility by regulating the expression of downstream pro-migration and pro-invasion genes, cyclin D1 (CCND1), MET, smoothened (SMO), and semaphorin 3C (SEMA3C)." (PMID 33917233, 2021). "In fact, in in vitro experiments, certain SMO inhibitors, such as cyclopamine, GDC-0449, LDE225, and HhA, have been preliminarily shown to exhibit a significant inhibitory effect on tumor growth and the metastasis of ARMS or transplanted tumor models." (PMID 34778066, 2021). "Expression levels of SMO, GLI1, and PTCH1 as assessed in tumor tissue by real-time quantitative polymerase chain reaction (qPCR) did not predict a response to the addition of vismodegib." (PMID 33498528, 2021). "We found 5 potential target genes (SKP2, SMO, SDCBP, FERMT2 and PGAM1) that were consistently predicted by the three softwares and involved in tumor-related signaling pathway." (PMID 34221971, 2021).
tumor (continued). "In aerodigestive cancer, the combined treatment with SMO and HDAC inhibitors promotes cell cycle arrest, suppresses SMO and PTCH1 expression, and delays tumor growth in an animal model, prolonging survival more than a single agent alone." (PMID 33396427, 2020). "In patient 9, SMO, NTRK3, IDH2, IGF1R, and CDK12 were also amplified in tumour #1 in addition to ERBB2 amplification." (PMID 31929516, 2020). "SMO can activate GLI to regulate target gene expression and affect migration/invasion, cell cycle, tumor growth, and cancer stem cells." (PMID 31979397, 2020). "In co-cultures, down-regulation of GLI1, SMO, and PTCH1 in the stroma correlated with reduced tumor growth rates in xenografted tumors and cell cultures, confirming a paracrine interaction." (PMID 31658643, 2019). "In our previous study, CYC loaded bovine serum albumin (BSA) nanoparticles showed effective and enduring tumor tissue accumulation and extracellular retention which increase binding of CYC and SMO membrane receptors." (PMID 31867309, 2019). "This paracrine mechanism is characterized by binding of tumor-secreted Hh ligands (SHH, Indian Hedgehog (IHH), or Desert Hedgehog (DHH)) to PTCH1 receptors, and elevated levels of GLI1, GLI2, PTCH1, and SMO genes in the tumor-adjacent stroma." (PMID 31658643, 2019). "When comparing upstream canonical HH-GLI inhibition (SMO inhibition) with downstream inhibition (GLI inhibition), it is evident that downstream inhibition is more effective in tumor therapy, as shown by several authors in recent studies." (PMID 30158435, 2018). "Decreased SMO expression in the pancreatic fibroblasts and expression of Shh in KPC-luc tumor cells was confirmed before injection." (PMID 30456390, 2018). "In the present study, we showed that a SMO inhibitor, AY9944 and a GLI-1 inhibitor, GANT61 improved the sensitivity for anti-cancer drugs in tumor ALI organoids." (PMID 29642386, 2018). "Treatment with the SMO inhibitor (SMOi) GDC-0449 (Vismodegib; 100 mg/kg/bid) slowed tumor growth, reduced metastatic burden and improved overall animal survival of M6-Hh tumors." (PMID 30042390, 2018). "The simulations suggested that upon an increase in SMO activity, the PI3K/Akt signalling plays a crucial role in promoting tumour proliferation." (PMID 29776351, 2018). "By applying PDEs inhibition, the control potential of SMO decreased and PI3K appeared as a significant factor in controlling tumour proliferation." (PMID 29776351, 2018). "Experiments in vitro with the cancer cell line, which was derived from this xenograft tumor, showed that the blockade of AXL and SMO, of SMO and EGFR, and, more efficiently, of AXL and EGFR was able to revert the resistance to EGFR." (PMID 28416737, 2017). "As the key regulators of Hedgehog pathway, SHH, SMO and GLI1 are upregulated in NSCLC tumor tissues compared to normal tissues." (PMID 28507311, 2017). "This tumor expressed higher levels of both phospho-AXL and SMO when treated with osimertinib, concomitantly with increased levels of vimentin and PDL-1." (PMID 28416737, 2017). "To investigate if the activating Hh and MET signals are the consequence of gene amplification, as previously demonstrated, we performed FISH analysis on resistant tumor samples, by the use of specific probes for MET and SMO genes." (PMID 28416737, 2017). "The human tumor data paralleled our cell line findings in that there was high PTCH1, SMO, GLI2, and GLI3 mRNA, but low GLI1 mRNA." (PMID 27793025, 2016). "SMO inhibition alters transcription factors GLI1 and GLI2 to remain inactive, which prevents the expression of tumor mediating genes within the Hh pathway." (PMID 25985215, 2015). "For example, the potent SMO inhibitor TAK-441, demonstrated decreased tumor growth in CRPC xenograft models." (PMID 26426053, 2015). "In other tumor types, GLI1 expression has been used to determine changes in Hh pathway activity and confirm targeted inhibition in patients treated with SMO inhibitors." (PMID 24598114, 2014).
tumor (continued). "A 3-bp insertion (69_70insCTG) in SMO, predicting an additional leucine residue in the signal peptide segment of SMO protein was also identified in LO68 cells and a MMe tumour." (PMID 23826113, 2013). "We addressed these questions by comparing tumor progression and spinal cord metastasis in a sporadic mouse model of SHH-MB in which rare GCPs are induced to express an oncogenic form of SMO, SmoM2, at postnatal day 0 (P0) and have deletion of one or both copies of Pten." (PMID 40766638, 2025). "SMO expression was significantly higher in all tumor types than in surrounding stroma, with no inter-tumor differences." (PMID 40542075, 2025). "Also, our study reveals crosstalk between HER2 and SMO: Combining trastuzumab with Hh inhibitors (Vis or Cyc) synergistically suppresses SMO, further inactivating AKT/mTOR signalling and enhancing anti-tumour effects." (PMID 40426308, 2025). "However, due to the high degree of tumor heterogeneity in advanced BCC, approximately 43% of BCC cases are resistant to SMO inhibitors such as vismodegib." (PMID 41383502, 2025). "Beyond canonical signaling axes, ALK may engage non-canonical mechanisms, such as aberrant activation of the Hedgehog/SMO-GLI axis, which has been observed in preclinical tumor models and may contribute to tumor stemness and resistance." (PMID 41614760, 2025). "Cyclopamine-competitive antagonists of SMO, like vismodegib and sonidegib, are approved for BCC patients with locally advanced or metastatic BCC unsuitable for surgery or radiation, helping control the disease and reducing tumor size." (PMID 41515948, 2025). "Here, tumor heterogeneity rather than the acquisition of secondary activating alterations represents a different mechanism of resistance to SMO inhibition." (PMID 41515948, 2025). "However, our results revealed a significant decrease in SMO and GLI‐1 protein levels in tumor tissues, suggesting that Rab23 plays a negative regulatory role in the SHH signaling pathway and can suppress tumor growth in HCC." (PMID 37884351, 2024). "Advanced HNSCC tumours were shown to express higher levels of SHH, PTCH1, SMO, GLI1, GLI2 and GLI3." (PMID 39234399, 2024). "Additionally, they found that high expression of SMO, along with a higher ratio of SMO mRNA to PTCH mRNA, significantly correlated with tumor size." (PMID 38730691, 2024). "Targeting SMO has emerged as a targeted treatment option for SHH-driven cancers including basal cell carcinoma and recurrent SHH-MB, demonstrating anti-tumor activity by suppressing SHH signaling." (PMID 39107797, 2024). "As expected, we found that Group3-MB tumor cells do not respond to SMO inhibition, while SHH-MB cells do." (PMID 39107797, 2024). "Liu S.J.’s research suggests that downregulation of the Rab 23 gene may enhance apoptosis, decrease tumor size, reduce the proliferation rate, and decrease the levels of SHH-related proteins (SMO and GLI-1) in Hep 3B cells." (PMID 38730691, 2024). "In contrast, numerous cell-based murine experiments have demonstrated the critical role of interactions between tumor cells and CAFs in tumor heterogeneity, with some clinical trials employing SMO inhibitors and non-specific TKIs yielding favorable outcomes." (PMID 37919751, 2023). "Surprisingly, more recent studies also observed that Shh deletion in the pancreatic epithelium, Smo deletion from stromal fibroblasts or chronic Hh inhibition using a SMO inhibitor accelerated PDAC progression and shortened survival, suggesting its tumor suppressor roles." (PMID 37213270, 2023).
tumor (continued). "Within tumor cells, the production of more Hh protein occurs through non-canonical activation pathways that are independent of SMO." (PMID 37919751, 2023). "In addition, AIM2 inhibited Gli1 expression through the smoothened homolog (SMO)‐independent pathway and regulated tumor cell proliferation and migration in a Gli1‐dependent manner." (PMID 36161280, 2023). "Moreover, inhibition of HH signaling by treatment with SMO inhibitor GDC-0449 attenuates cell growth and migration in HCC cell lines and delays tumor development in HBx transgenic mice and xenograft-bearing nude mice." (PMID 35464958, 2022). "Consistent with the low SMO activity driving LY6D+ accumulation, human rBCCs containing high levels of SMO activity through activating mutations lacked spontaneous LY6D+ tumor accumulation." (PMID 36473848, 2022). "In addition to DYRKi, the MKL1 inhibitor CCG-1423 was reported to inhibit the tumor growth and GLI1 expression in SMO inhibitor-resistant cell lines." (PMID 35163655, 2022). "The results showed that tumor tissues from EGFR TKI-resistant patients had significantly increased GLI1, SMO, BCL2, and SNAIL protein levels compared with those from TKI-sensitive cases, suggesting that these proteins are possibly related to TKI resistance in NSCLC." (PMID 35154464, 2022). "Although cyclopamine is known to be very specific in targeting SMO in the hedgehog pathway, it is important to note that cyclopamine has been shown to induce tumor cell apoptosis independent of SMO." (PMID 36230980, 2022). "Increased expression of SMO and GLI1 was directly correlated to a larger tumor size." (PMID 33440657, 2021). "Indeed, inhibitors of the SHH pathway effector SMO have been successfully tested in both in vitro and in vivo GBM models and demonstrated to efficiently counteract self-renewal and tumor progression." (PMID 34439999, 2021). "In addition, the presence of a functional stromal microenvironment enhances tumor growth in vivo, along with activating the angiogenetic process in an HH-dependent manner and with making CCA cells more sensitive to SMO-antagonizing compounds." (PMID 34638259, 2021). "In the mouse model of PDAC, SMO-independent GLI1 activation promotes transformation and requires both TGFβ and KRAS signaling where inhibition of TGFβ by TbRI antagonist SD208 significantly reduces tumor burden and increases infiltration of lymphocytes." (PMID 34113570, 2021). "A patient (No. 10) whose tumor had copy number loss of the CRLE2 and SMO genes did not carry other somatic gene mutations nor germline pathogenic variants." (PMID 33854152, 2021). "However, canonical SMO-dependent SHH signaling, as mediated by GLI1 nuclear localization, downregulates WNT signaling and tumor cell differentiation." (PMID 31979397, 2020). "Expression of SMO was observed in DCIS and IBC but not in normal tissue, correlated with tumor size, lymph node involvement and increased risk of recurrence (, but not with histological grade or other clinically relevant markers." (PMID 31027259, 2019). "Down-regulation of GLI transcriptional factors (GLI1 or GLI2), but not SMO signaling inhibition, reduces tumor sphere formation, a characteristics of tumor initiating cell (TIC)." (PMID 30382189, 2019). "Topical treatment of BCC with forskolin decreases tumor growth and reduces GLI1 mRNA level in an inducible SMO-mutant BCC mouse model, providing evidence that forskolin inhibits growth of BCCs resistant to SMO inhibitors." (PMID 30934935, 2019).
tumor (continued). "Finally, we observed SMO, LRP, CSKNK2A2, DVL, TEAD, NOTCH1 and KLF4 mutated genes, which are crucial in the regulation of Wnt, Notch and Hedgehog signalling pathways and thus could be the possible culprit behind the enrichment of CSCs in tumour and distal margin." (PMID 30950180, 2019). "In summary, using a clinically approved and widely employed SMO inhibitor in both the Hesx1Cre/+;Ctnnb1loxex3/+ mice and a human xenograft model, our research demonstrates that the inhibition of the SHH pathway has a tumour-promoting effect." (PMID 30645190, 2019). "Parallel activation of FGFR and SMO in ex vivo tumor cell-cerebellum slice co-cultures reduced invasion of tumor cells without affecting proliferation." (PMID 31835472, 2019). "Examination of main Hh target genes individually shows higher levels of GLI2, PTCH1, SMO, BOC, and HHIP transcripts in the tumor-adjacent tissue as compared to the bulk tumor, further supporting the importance of the tumor-adjacent tissue in the activity of Hh signaling." (PMID 31658643, 2019). "The development of resistance towards SMO inhibitors in cancer has been also related to the existence of residual tumor cells that drive tumor regrowth with a mechanism that no longer relies on HH signaling for survival." (PMID 30558232, 2018). "SMO antagonists that are FDA-approved for the management of metastatic BCC (Vismodegib and Sonidegib) are able to restore homeostatic levels of signaling and blunt tumor growth." (PMID 29348431, 2018). "Allograft tumours, derived from cultured mouse MB cells, do not harbour an active HH pathway and they fail to respond to SMO inhibitors." (PMID 30068568, 2018). "These cells are characterized by a most permissive chromatin state that allows the activation of WNT signaling rather than de novo mutations, thus highlighting the importance of combination therapy with both SMO and WNT inhibitors to overcome tumor relapse in BCC." (PMID 30558232, 2018). "Data obtained using human tumour cell lines treated with SMO inhibitors were not predictive in the clinic because the HH pathway was suppressed in cell culture." (PMID 30068568, 2018). "Among the components of Hh signaling, it has been reported that deletion of SMO, a component of SHH–PTCH1–SMO autocrine signaling, did not affect multistage tumor development of PDAC." (PMID 30423843, 2018). "Analysis of the simulations suggested that a combined inhibition of SMO and the PI3K/Akt signalling pathway may provide an effective reduction in tumour proliferation." (PMID 29776351, 2018). "In this respect, we previously reported that the combined inhibition of both SMO and MET exerted a significant anti-proliferative and pro-apoptotic effect in this model in vitro and in vivo, with tumor regressions and complete response in 100% of HCC827-GR tumors xenografted in nude mice." (PMID 28416737, 2017). "Next, IHC was performed to measure the expression of SMO, GLI1, and KI67 in tumor tissue." (PMID 29254217, 2017). "The only single tumor resistant to afatinib plus cetuximab, and then refractory to both osimertinib and chemotherapy, showed AXL activation along with an increased expression of SMO after treatment with osimertinib." (PMID 28416737, 2017). "In addition, cotreatment of SMO inhibitor and MET inhibitor to HCC827-GR xenografted tumors further suppressed tumor volume, since constitutive MET activation was observed in HCC827-GR cells." (PMID 28105432, 2016). "A follow-up study showed that while SMO inhibition in a genetic mouse model of PDAC resulted in decreased tumor stroma, the tumor itself was more aggressive, more highly vascularized, and more poorly differentiated, resulting in lower survival rates than controls." (PMID 26891329, 2016). "Treatment with IPI-926, a SMO inhibitor, significantly decreased the TCM-mediated induction of BMP4 transcription and BMP4 protein levels suggesting activation of BMP4 expression is via tumor cell produced HH ligands." (PMID 26755648, 2016).